DMP1 (dentin matrix acidic phosphoprotein 1)
Diseases named in the same sentence as DMP1 in open-access papers (continued):
Sharing a sentence is not in itself a finding about the gene and the disease.
osteoarthritis (3 papers, 2010 to 2024). A noninflammatory degenerative joint disease occurring chiefly in older persons, characterized by degeneration of the articular cartilage, hypertrophy of bone at the margins and changes in the synovial membrane. "It remains unknown, however, whether heterozygous carriers of the DMP1 mutation have an increased risk of developing early degenerative arthritis." (PMID 20499351, 2010). "The mechanism leading to the degenerative joint disease and ankylosis is unclear, but occurrence of these findings may indicate that DMP1 is required for normal long-term articular cartilage health." (PMID 20499351, 2010). "Our finding that inducible Dmp1 deletion led to increased vessel activity also in subchondral bone suggests that extracellular DMP1 may protect articular cartilage from vessel invasion, which accompanies neoinnervation of the tissue and sensation of pain in osteoarthritis patients." (PMID 35650194, 2022).
periodontal diseases (3 papers, 2019 to 2022). "Localization of DMP1 in dentin and cementum is related to mineralization and its deletion leads to increased susceptibility to periodontal diseases in mice, suggesting that DMP1 is essential for the formation and maintenance of a healthy periodontium." (PMID 30863409, 2019).
Raine syndrome (3 papers, 2017 to 2025). "Taken together, we postulate that the lack of proper phosphorylation in and/or the reduction of DMP1 may be one of the contributing factors in causing the rachitic phenotypes in the Fam20C-cKO mice and in some human patients with Raine syndrome." (PMID 28620244, 2017).
secondary hyperparathyroidism (3 papers, 2015 to 2021). Overproduction of parathyroid hormone in response to influence external to the parathyroid glands. "Elevated serum PTH levels might be indicative of a secondary hyperparathyroidism-like state, which may contribute to the accelerated bone loss in Dmp1-PPRKO mice." (PMID 34968192, 2021). "Therapy with doxercalciferol increases expression of full-length FGF23 as well as total DMP1 and decreases the presence of the 57 kDa DMP1 fragment in the bone of pediatric dialysis patients with secondary hyperparathyroidism." (PMID 25774916, 2015).
melanoma (2 papers, 2021). A malignant, usually aggressive tumor composed of atypical, neoplastic melanocytes. "Likewise, PTEN, Dmp1, and Bax are upregulated with 4.82, 4.7 and 3.35 folds in B16-F0 melanoma." (PMID 34680491, 2021).
van Buchem disease (2 papers, 2021 to 2025). "Deletion of an SOST regulatory element causes van Buchem disease (OMIM 239100) and inactivating mutations in DMP1, the gene encoding dentin matrix acidic phosphoprotein 1, cause autosomal recessive hypophosphataemia (OMIM: 241,520)." (PMID 40462134, 2025).
bone-mineral disorders (1 paper, 2014). "We used a 4.2 kDa peptide (SPR4) that binds to ASARM-peptide/motif to study the DMP1-PHEX interaction and to assess SPR4 for the treatment of energy metabolism defects in HYP and potentially other bone-mineral disorders." (PMID 24839967, 2014).
colon cancer (1 paper, 2014). "DMP-1 is known to contribute to the invasion of colon cancer cells in a RGD-independent manner by bridging MMP-9 to CD44." (PMID 25396425, 2014).
cyst (1 paper, 2022). A sac-like closed membranous structure that may be empty or contain fluid or amorphous material. "Nuclear accumulation of β-catenin was detected in the cyst wall and solid nest, and cell nuclei comprising dentinoid material deposition were positive for dentin matrix protein-1 (DMP1), suggesting osteoblastic differentiation in the mineralised bone or dentin." (PMID 35443664, 2022).
deafness (1 paper, 2023). An inherited or acquired condition characterized by the complete loss of the ability to hear from one or both ears. "In addition, Dentin Sialophosphoprotein (DSPP), another member of the SIBLING proteins (DSPP and DMP1 share many similarities in both their gene and protein structures), is from a known deafness gene (DFNA39) that can cause congenital sensorineural deafness." (PMID 37106825, 2023). "Dmp1 may be a suitable target molecule for the treatment of deafness, and our study provides strong support for gene therapy for sensorineural deafness." (PMID 37106825, 2023). "Moreover, the inclusion among the DEGs of genes involved in inner ear development and deafness (Atoh1, Edn1, Hes1, Kl, Myc, Mycn and Olig1) suggested their interaction with Dmp1 in these processes." (PMID 37106825, 2023).
diabetes (1 paper, 2024). "Furthermore, deletion of Vhl in late osteoblasts and osteocytes by Dmp-1-Cre partially improved glucose metabolism in STZ-induced diabetes." (PMID 38945950, 2024).
Hypoglycemia (1 paper, 2024). A decreased concentration of glucose in the blood. "Consistent with the phenotypes observed in the Ocn-Cre;Vhlflox/flox mice, the Dmp-1-Cre;Vhlflox/flox mice also had a lean appearance, hypoglycemia, and improved glucose tolerance, without any changes in serum insulin levels or pancreatic β cells." (PMID 38945950, 2024).
Insulin resistance (1 paper, 2024). Increased resistance towards insulin, that is, diminished effectiveness of insulin in reducing blood glucose levels. "This suggests that DMP1-Cre–mediated ablation of TβRII mitigates HFD-induced insulin resistance." (PMID 39171528, 2024).
kidney transplant (1 paper, 2015). A surgical procedure in which one or both kidneys from a donor are implanted into a recipient. "Whether this finding reflects an interaction between immunosuppressive agents and CKD remains to be determined; however, it is interesting to note that serum phosphorus levels were lower in kidney transplant recipients and phosphorus has been shown to stimulate DMP1 expression." (PMID 26390291, 2015).
lung squamous cell carcinoma (1 paper, 2025). "DMP1, GP1BA and HEPH remained associated with lung squamous cell carcinoma." (PMID 41340014, 2025).
lymphoma (1 paper, 2008). A malignant (clonal) proliferation of B- lymphocytes or T- lymphocytes which involves the lymph nodes, bone marrow and/or extranodal sites. "K-rasLA lung tumors are different from Eμ-Myc lymphomas in that neither bi-allelic Arf deletion or Mdm2 overexpression were found in any tumors, regardless of the genotype of Dmp1." (PMID 21892281, 2008).
lymphopenia (1 paper, 2022). Reduction in the number of lymphocytes. "Similarly, conditional ablation of the osteocyte population using transgenic mice engineered to express the diphtheria toxin receptor under the dentin matrix protein 1 (Dmp1) promoter indirectly induced lymphopenia by depleting lymphoid-supportive stroma in the BM." (PMID 35565219, 2022).
malnutrition (1 paper, 2013). Inadequate nutrition resulting from poor diet, malabsorption, or abnormal nutrient distribution. "It is currently unclear whether Dmp1 is involved in hypoxic response, osmotic pressure, malnutrition signaling, or hormonal signaling." (PMID 24205004, 2013).
myelofibrosis (1 paper, 2022). A partial or complete replacement of the bone marrow stroma by fibrous tissue. "To further identify the stromal cell population responsible for myelofibrosis, we used a Dmp1-Cre transgene that targets osteoblasts and approximately 30% of CAR cells, which we previously showed are enriched for osteolineage genes." (PMID 35439167, 2022). "Interestingly, a similar degree of myelofibrosis, as measured by reticulin staining and Col3a1 mRNA expression, was observed in control and Dmp1-Cre Tgfbr2fl/fl recipients." (PMID 35439167, 2022). "Specifically, we show that abrogation of TGF-β signaling in Osx-Cre–targeted, but not Dmp1-Cre–targeted stromal cells, prevents the development of myelofibrosis." (PMID 35439167, 2022).
myeloma (1 paper, 2019). "The inductive effects of the plant-produced DMP1 were comparable to the effects of commercial hDMP1 produced in a mouse myeloma cell line (R&D Systems, USA), supporting the concept that plant-produced protein can influence cellular behavior similar to the protein produced from mammalian cells." (PMID 31816999, 2019).
oral disease (1 paper, 2023). "The following study addresses this persistent oral disease by further investigating the effect of DMP1 expression on the differentiation of XLH dental pulp cells." (PMID 36849506, 2023).
pulpitis (1 paper, 2025). Inflammation of the dental pulp. "Some generated a transgenic mouse model which conditionally overexpressed TNF-α, and bred these mice with a dentin matrix protein 1 (DMP1)-Cre line for overexpression of TNF-α solely in the tooth pulp and bone, forming pulp inflammation resembling pulpitis." (PMID 40351786, 2025).
retina tumour (1 paper, 2022). "DMP1 appeared to be a promising candidate because of its reported angiogenesis-modulating activity in a retina tumour model." (PMID 35650194, 2022).
sarcopenia (1 paper, 2022). Progressive decline in muscle mass due to aging which results in decreased functional capacity of muscles. "However, our histology finding of no obvious changes in the total number of nuclei of muscle in partial ablation of DMP1-positive osteocytes suggested that the sarcopenia and muscle atrophy phenotype is most likely caused by the disturbance of osteocyte-muscle crosstalk." (PMID 36305580, 2022). "This has led us to suggest that sarcopenia may be caused directly by the Dmp1 expression in muscle." (PMID 36305580, 2022).
Splenomegaly (1 paper, 2022). Abnormal increased size of the spleen. "As expected, similar alterations in peripheral blood counts, splenomegaly, and bone marrow cellularity were observed in control and Dmp1-Cre Tgfbr2fl/fl recipients of MPLW515L-transduced HSPCs." (PMID 35439167, 2022).
synovial sarcoma (1 paper, 2020). "The six unshared genes (CEBPB, BMP6, PTGS2, DMP1, FGF2, and H2AFV) are likely the important contributors to the ossifying phenotype seen in the metastatic synovial sarcomas." (PMID 32290096, 2020).
uremia (1 paper, 2022). A clinical syndrome associated with the retention of renal waste products or uremic toxins in the blood. "In addition, uremia induced suppression of DMP1, and hence increments of FGF23 may explain the clinical observation that in more early stages of CKD, FGF23 and phosphate levels appear to diverge, pointing to another inducer of FGF23 than phosphate itself, namely suppressed DMP1." (PMID 35629904, 2022).
tumor (22 papers, 2008 to 2026). "Data obtained have shown that DMP-1 is expressed in breast and lung cancers and has significant inverse associations with tumor grades." (PMID 36765749, 2023). "Conversely, expression of transcripts encoding the tumor suppressors Dmp1 and Foxj1 was suppressed by Src and increased by contact normalization." (PMID 35177067, 2022). "Dmp1-deficient mice were prone to spontaneous tumor development, which was accelerated when the animals were neonatally treated with ionizing radiation or dimethylbenzanthracene." (PMID 33120969, 2020). "The wild type Dmp1 allele was retained and expressed in tumors arising from Dmp1+/- mice, demonstrating a haplo-insufficiency of Dmp1 in tumor suppression." (PMID 33120969, 2020). "The Dmp1+/- tumors often retain wild type allele of DMP1, thus DMP1 is haplo-insufficient for tumor suppression." (PMID 19671193, 2009). "To probe mechanisms underlying DKK3's tumor‐suppressive role in acinar cells, we performed pre‐ranked GSEA on the DD versus WT RNA‐seq data, which highlighted MAPK, JUN, and DMP1 pathways, with Fos emerging as a key regulator." (PMID 41147409, 2026). "DMP-1 can induce expression of VE-cadherin, followed by inhibition of VEGFR-2 phosphorylation and Src-mediated signaling, and, therefore, reduce tumor-associated angiogenesis." (PMID 36765749, 2023). "Western blot was used to identify the EVs classical marker of Tumor Susceptibility Gene 101 (TSG101), and measure the amount of osteocyte‐specific protein Dentin Matrix Protein 1 (DMP1) in plasma EVs." (PMID 35508803, 2022). "DMP1 plays a role in providing cell autonomous tumor surveillance, which bring about the senescence or apoptosis of cancer cells to prevent the development of cancer." (PMID 35366382, 2022). "Although Dmp1-deficient mice develop a broad spectrum of epithelial and non-epithelial tumors, lung tumors were the most frequently encountered neoplasms in both Dmp1-null and Dmp1-hetrozygous mice." (PMID 33120969, 2020). "H-RasV12 expression results in tumorigenic phenotypes, and the delay in replicative senescence of Dmp1-null MEFs have been observed, suggesting that DMP1 functions as a tumor suppressor by increasing ARF expression." (PMID 32759846, 2020). "DMTF1, also known as cyclin D-binding myb-like protein-1 (Dmp1), is a well accepted tumor suppressor." (PMID 25965824, 2015). "Both Dmp1−/− and Dmp1+/− mice were prone to tumor development when newborn pups were treated with dimethylbenzanthracene or ionizing radiation." (PMID 24205004, 2013). "Again the tumor-reducing effect was highest in strain 79, lowest in strain 138, suggesting that the effect of Dmp1 is dose-dependent." (PMID 24205004, 2013). "This suggests that either cells expressing Flag-Dmp1 stopped proliferating or only tumor cells that succeeded in downregulating Flag-Dmp1 protein were growing." (PMID 24205004, 2013).
tumor (continued). "Molecules that specifically activate the Dmp1 promoter or the Dmp1α protein will be effective novel chemotherapeutic agents to induce regression of tumor growth in vivo." (PMID 24205004, 2013). "Judging from the tumor spectra of Dmp1-knockout mice, it should be involved in a variety of malignancies." (PMID 21892281, 2008). "On the other hand, Dmp1-knockout mice are prone to tumor development, especially lung adenocarcinomas." (PMID 21892281, 2008). "Consistently, we observed numerous areas of Ki67(+) Flag-Dmp1(−) cells (shown in stars), supporting our hypothesis that inactivation of the Flag-Dmp1 transgene is necessary for tumor cell proliferation." (PMID 24205004, 2013). "The function of human DMP1 protein (the transcription factor that is involved in the oncogene-tumor suppressor signaling) is an unexplored area in human cancer, and it remains to discover its post-translational modifications and identification of DMP1-protein binding partners." (PMID 19671193, 2009). "Moreover, DMP1-mediated inhibition of angiogenesis in bone may be useful in arresting growth of tumours including osteo- and chondrosarcomas." (PMID 35650194, 2022). "Among them, DMP1 impairs VEGF-mediated angiogenesis, while BSP and OPN promote angiogenesis in tumor progression." (PMID 39922489, 2025). "Dmp1 not only delayed HER2/neu-driven mammary carcinogenesis, but also decreased tumor volumes when the animals were sacrificed." (PMID 24205004, 2013). "To further investigate the mechanisms of decreased Flag-Dmp1 expression in MDTG;neu tumors, we extracted genomic DNA from matched tail and tumor samples and calculated Flag-Dmp1 gene copy numbers by real-time PCR." (PMID 24205004, 2013). "In our IHC studies, we observed that the Flag-Dmp1α and Ki67 protein expression were mutually exclusive, suggesting that Flag-Dmp1-positive areas were not proliferating and thereby preventing tumor progression in vivo." (PMID 24205004, 2013).
cancer (12 papers, 2004 to 2025). A tumor composed of atypical neoplastic, often pleomorphic cells that invade other tissues. "It is known that loss of DMP1 caused spontaneous tumorigenesis in mice and death by 24 months of age from different forms of cancer." (PMID 19671193, 2009). "How far anthracycline resistance is mediated by Dmp1 in cancer cells remains to be elucidated." (PMID 38835346, 2024). "However, DMP1 was found to be significantly elevated in different cancer types." (PMID 36081907, 2022). "Likewise, it will be possible to prevent cancers by stimulating the Dmp1 activity or increasing its protein levels/activity without causing toxic effects of accelerated aging." (PMID 24205004, 2013).
adenocarcinoma (3 papers, 2008 to 2025). A common cancer characterized by the presence of malignant glandular cells. "In fact, we have found that tumors that showed deletion of Dmp1 tended to show the phenotype of adenocarcinomas (5/7, 71%)." (PMID 21892281, 2008).
infection (3 papers, 2021 to 2023). The state of being infected such as from the introduction of a foreign agent such as serum, vaccine, antigenic substance or organism. "At 1month post‐infection, the impact of DMP1‐shRNA injection on cognitive functions was tested in SAMP8 mice." (PMID 35366382, 2022). "We found Satb2 overexpression infected with Ad‐Satb2 slightly promoted Dmp1 and Dspp expression on day 3 and markedly upregulated on day 7, which was inhibited by knockdown of Satb2 expression with Ad‐siSatb2 infection." (PMID 33660290, 2021).
bone disorder (2 papers, 2023 to 2024). "Our data suggest that combined DMP1 repletion and FGF23 blockade could effectively correct ARHR-associated mineral and bone disorders." (PMID 37943605, 2023). "The study proposed that simultaneous restoration of DMP1 levels and inhibition of FGF23 could effectively rectify mineral and bone disorders associated with ARHR." (PMID 38956429, 2024). "Therefore, our data support a potential therapeutic advantage of combined DMP1 repletion and FGF23 blockade to effectively correct ARHR-associated mineral and bone disorders." (PMID 37943605, 2023).